TENM4 (teneurin transmembrane protein 4)
Diseases named in the same sentence as TENM4 in open-access papers (continued):
Sharing a sentence is not in itself a finding about the gene and the disease.
TENM4 also shares sentences with these, for which no sentence is quoted: mental disorder (4 papers); autism (3); neurodevelopmental disorder (2); Parkinson disease (2); serous ovarian tumors (2); triple-negative breast carcinoma (2); Anorexia (1); Asperger syndrome (1); asthma (1); Ataxia (1); brain ischemia (1); cancer of the pancreas (1); cataract (1); chronic lymphocytic leukemia (1); CNS DLBCL (1); Cognitive impairment (1); colorectal tumors (1); depression (1); diabetes (1); esophageal carcinoma (1); hepatocellular carcinoma (1); Intellectual disability (1); invasive carcinoma (1); lipoma (1); liver cancer (1); melanoma (1); mood disorder (1); movement disorder (1); myocardial ischemia (1); neurological disorders (1).
A further 4 diseases each share a sentence with TENM4 in 1 paper.